CXCL9 (C-X-C motif chemokine ligand 9)
Diseases named in the same sentence as CXCL9 in open-access papers (continued):
Sharing a sentence is not in itself a finding about the gene and the disease.
autoimmune disease (continued). "Among them, CXCR3 and its chemokines CXCL10, CXCL9, and CXCL11 are widely involved in the pathogenesis of autoimmune diseases such as HT, GD, thyroid eye disease (TED), type 1 diabetes, and autoimmune Addison’s disease, and may be potential targets for new drugs to treat these diseases." (PMID 35720300, 2022).
malaria (26 papers, 2009 to 2025). Malaria is a serious and sometimes fatal disease caused by a parasite that commonly infects a certain type of mosquito which feeds on humans. "We show during malaria age is associated with increased inflammatory chemokines CCL2, CCL3, CXCL8, CXCL9, along with CRP, and IDO, which associate with symptoms." (PMID 41027884, 2025). "Distinct cytokine profiles in malaria and HIV coinfections compared to malaria monoinfections were increased IL-12, CXCL9, CXCL11, IL-18, and G-CSF levels and decreased TNF and IL-4 levels." (PMID 36716305, 2023). "The data also highlights IL-10 and CXCL9 as important factors in both asymptomatic and acute malaria and add to the understanding of asymptomatic P. falciparum infections in malaria-endemic areas." (PMID 33407502, 2021). "Comparable to the findings in this study, mDCs from malaria-naïve individuals secrete high levels of CXCL9 and CXCL10 in response to the parasite in vitro." (PMID 33407502, 2021). "The Th1-associated chemokines CXCL9 and CXCL10 exhibited a robust increase in plasma levels during acute malaria." (PMID 33407502, 2021). "CXCL9 and IL-4 were the top markers when we analyzed asymptomatic malaria vs. controls, whereas IL-6 and CXCL10 were highlighted when symptomatic vs. asymptomatic malaria patients were compared." (PMID 34727121, 2021). "Increased levels of CXCL8 and CXCL9 as well as reduced levels of CCL5 (also known as RANTES) have been observed in severe malaria patients." (PMID 24476686, 2014). "Although the exact mechanism of these chemokines in malaria pathogenesis is unknown, increased levels of chemokines such as CXCL9, CXCL10, and CXCL11 have been proposed as predictive markers for HIV disease progression." (PMID 36716305, 2023). "Seven studies investigated the effect of IPTp-SP, whereas the remaining four investigated adverse pregnancy outcomes associated with submicroscopic placental malaria, infection with P. falciparum and measures of placental malaria and CXCL9 response to malaria during pregnancy." (PMID 34429121, 2021). "mDCs from malaria-exposed adults also secreted the Th1-associated chemokines CXCL9 (MIG) and CXCL10 (IP-10) as well as CCL2 but no CCL5." (PMID 33407502, 2021). "Indeed, the macrophage inflammatory protein MIP3-α/CCL20 and the monokine induced by interferon-gamma MIG/CXCL9 were found elevated in infants with severe malaria and in patients with atopic dermatitis." (PMID 25698903, 2015). "This study aimed to investigate whether and how the plasma concentrations of eight soluble bio-molecules, namely Neopterin, sCD163, suPAR, Pentraxin3, sCD14, Fractalkine/CX3CL1, sTREM-1 and MIG/CXCL9, differ among young patients presenting with distinct clinical manifestations of malaria." (PMID 27357958, 2016). "The high connectivity exhibited by CXCL9 may be indicative of an important role for this chemokine in exposed but non-infected individuals since it correlates with protection against malaria in volunteers vaccinated by the circumsporozoite protein-based vaccine." (PMID 23433077, 2013). "In humans, malaria during pregnancy results in elevated levels of numerous cytokines, including IFN-γ, TNF-α, IL-4, IL-6, IL-10, and CXCL9 in peripheral circulation, with some of these cytokines linked to increased risk of pregnancy loss." (PMID 40470930, 2025). "CXCR3 ligands, CXCL9-11, upregulate in mouse liver sinusoidal endothelial cells (LSECs) and mediate effector CD8+ T cell homing to the liver during malaria liver-stage infection." (PMID 37056783, 2023). "They demonstrated that malaria and L. loa co-infections had decreased levels of C-X-C motif chemokine 5 (CXCL5) and comparable levels of CX3CL1, CXCL7, CXCL9, CXCL11, and CCL28 compared with malaria monoinfection." (PMID 36269701, 2022).
malaria (continued). "Using information from the canonical coefficients, we found that the IFN pathway exhibited a relevant role in the discrimination of symptomatic malaria and controls, with CCL2 followed by CXCL10 and CXCL9 as the top markers." (PMID 34727121, 2021). "The markers forming the first cluster tended to increase the MDP values in the group of symptomatic malaria, with remarkable high values of TNF-α, IL-6, CXCL9, AST, CRP, IL-8 and ALT." (PMID 34727121, 2021). "Malaria-induced MO-DCs possess a strong phagocytic activity, capacity to cross-present antigens to CD8+ T cells and express high levels of CXCL9, CXCL10 and the chemokine receptor CCR5." (PMID 27808089, 2016). "The relative involvement of the 3 CXCR3 chemokines (CXCL9, CXCL10 and CXCL11) in the recruitment of inflammatory leucocytes to the brain of malaria-infected mice has been extensively investigated." (PMID 24476686, 2014). "Chemokine release is also associated with the malaria blood stage, but HZ alone did not induce the secretion of any of the chemokines investigated, CXCL8 (IL-8), CXCL9, CXCL10, CCL2 and CCL5." (PMID 40717771, 2025). "Severe malaria patients exhibit high levels of serum pro-inflammatory cytokines (TNF, IL-1β, IL-6, IL-8, IL-12, IFNγ) and chemokines (CCL2, CCL5, CXCL9, CXCL10), and lower levels of regulatory cytokines (IL-10, TGFβ, PGE2) compared to those with mild and asymptomatic malaria." (PMID 27792766, 2016). "The results show that in early malaria, selected immune response-related genes were up-regulated including α β and γ interferon-related genes, as well as genes of IL-15, CD36, chemokines (CXCL10, CCL2, S100A8/9, CXCL9, and CXCL11), TRAIL and IgG Fc receptors." (PMID 24188121, 2013). "In the group of individuals presenting with severe non-lethal malaria, parasitaemia displayed significant positive associations with TNF, sTNF-RI, IFN-γ, IL-10, CXCL9, CXCL10, SOD-1 and HO-1, while negatively correlated with the chemokines IL-8 and CCL2." (PMID 23433077, 2013). "Consistent with this link, Vδ2+ γδ T cells from malaria-naive adults have higher frequencies of IFNγ and TNF-producing cells in response to malaria in vitro stimulation compared to children and circulating CXCL9 was correlated with age in patients with malaria." (PMID 41027884, 2025). "In addition to producing type I IFNs, DCs produce a wide range of pro-inflammatory cytokines, including TNF-α, IL-12, and IL-6, and chemokines, such as CXCL1, CXCL2, CCL2, CCL5, CXCL9, and CXCL10 in response to malaria parasites, and play crucial roles in malaria immunity and pathogenesis." (PMID 30619355, 2018). "Here we show that during mouse malaria, splenic inflammatory monocytes differentiate into monocyte-derived dendritic cells (MO-DCs), which are CD11b+F4/80+CD11c+MHCIIhighDC-SIGNhighLy6c+ and express high levels of CCR5, CXCL9 and CXCL10 (CCR5+CXCL9/10+ MO-DCs)." (PMID 27808089, 2016). "However, for the malaria group, four distinct correlation patterns were observed; first pattern (CCL4, CCL2, CCL3, IL12 and IL2), second pattern (IL-17A, IL-1β, CCL11, IL4), third pattern (IL5, IL7, IL13), and fourth pattern (IL1RA, CXCL10, TNFα, IL2R, CXCL9, IL6)." (PMID 35811678, 2022).
rheumatoid arthritis (26 papers, 2012 to 2025). A chronic, systemic autoimmune disorder characterized by inflammation in the synovial membranes and articular surfaces. "Among the cytokines that were differentially expressed, we observed downregulation of CXCL9, whose upregulation has been associated with the development of rheumatoid arthritis-associated B-cell lymphoma." (PMID 41008822, 2025). "The same conclusions were drawn in a related study on the microarray analysis of gene expression in rheumatoid arthritis joints performed using cDNA microarrays and laser microdissection: CXCL9 and CXCL10 upregulation in the synovial lining associated with inflammation." (PMID 35734177, 2022). "CXCL9 serves as a biomarker of rheumatoid arthritis activity, regulated by IFN-γ and proinflammatory cytokines, which exacerbate synovial inflammation and joint damage." (PMID 40650062, 2025). "CXCL9, acting as a ligand for CXCR3 expressed in synovial mast cells and eosinophils, has been associated with inflammation in synovial tissues and rheumatoid arthritis pathogenesis." (PMID 38650940, 2024). "CXCL9 gene and protein expression were higher in proportion in the synovium of rheumatoid arthritis patients than that in osteoarthritis patients in a previous study." (PMID 35734177, 2022). "The cytokine–cytokine receptor interaction pathway and the increased expression of Cxcl9 and Cxcl10 are related to the development of rheumatoid arthritis." (PMID 35911717, 2022). "In rheumatoid arthritis (RA), high CXCR3 expression on mast cells is associated with CXCL9 and CXCL10 expression in synovial fluid from RA patients but not in traumatic arthritis or osteoarthritis patients." (PMID 36275816, 2022). "Mast cells preferentially express CXCR3 protein in patients with rheumatoid arthritis and, importantly, this expression is accompanied by elevated level of CXCL9 and CXCL10." (PMID 24278169, 2013). "Moreover, the expression of CXCL9 was increased in the joints of patients with rheumatoid arthritis and it was found that activation of spinal CXCL9 mediated bone cancer pain in rats." (PMID 25789329, 2015). "Serum samples from 49 patients diagnosed with pSS, 33 patients with rheumatoid arthritis (RA), and 30 healthy controls (HCs) were collected for measurements of CXCL9, CXCL10, CXCL11, and CXCR3." (PMID 38900301, 2024). "In addition, CXCL9 expression is also elevated in the joints of patients with rheumatoid arthritis." (PMID 34681732, 2021). "CD109 facilitates the activation and recruitment of leukocytes by promoting the production of CXCL-9 and CXCL-10 in rheumatoid arthritis FLSs." (PMID 39990858, 2024). "In a previous study, it was discovered a notable correlation between NT‐proBNP and CXCL9, an inflammatory chemokine that has a crucial role in the pathogenesis of rheumatoid arthritis (RA) and recently has also been introduced as a pivotal contributor to impaired cardiac and vascular function." (PMID 39160453, 2024). "Mechanistically, these expanded inflammatory Thy1+ fibroblasts were shown to drive inflammation in rheumatoid arthritis by secreting IL6 and chemokines such as CCL2, CX3CL1, CXCL9, and CXCL12." (PMID 35085231, 2022). "Similar to rheumatoid arthritis, in arthritis-irAE, SF T cells highly expressed CXCR3 and CXCR6, and their matching ligands, CXCL9/10/11, and CXCL16 were mainly produced by myeloid cells." (PMID 35413951, 2022). "More recent evidence has demonstrated increased levels of CXCL8, CXCL9, CXCL10, and CCL20 in rheumatoid arthritis, indicating the importance of chemokines in inflammatory bone diseases." (PMID 33510341, 2021). "T cell CXCR3 and its ligands CXCL9 and CXCL10 as well as CCR5 and its ligands CCL3 and CCL5 are expressed at higher levels in disorders where Th1 immune responses predominate such as multiple sclerosis and rheumatoid arthritis." (PMID 36670847, 2023).
rheumatoid arthritis (continued). "The proinflammatory cytokines such as IL-1β, IL-6, TNF, CXCL9, CXCL10, and IFN-γ participate in the pathology of several chronic inflammatory diseases including rheumatoid arthritis, coronary diseases, cerebral malaria, tegumentary leishmaniasis, and Chagas diseases." (PMID 32385802, 2020). "The expression of CXCL9 and CXCL10 is also increased in the joints of patients with rheumatoid arthritis suggesting that these chemokines may contribute to the joint pathology associated with the disease." (PMID 24947159, 2014). "Moreover, studies in patients with rheumatoid arthritis (RA) showed that fibroblast-like synoviocytes (FLS) constitutively express CCR2, CCR5, CXCR3,and CXCR4; in addition, stimulation with CCL2, CXCL12, CXCL9, and CXCL10 enhances FLS migration and proliferation." (PMID 28883822, 2017).
tuberculosis (26 papers, 2009 to 2026). A chronic, recurrent infection caused by the bacterium Mycobacterium tuberculosis. "In addition, four genes, namely, IFN-γ, IP-10, IL2R, and CXCL-9, were strongly expressed and demonstrated a high diagnostic potential for tuberculosis." (PMID 32962082, 2020). "Drug-resistant tuberculosis was related to miR-548 m, miR-631, miR-328-3p, and miR-let-7e-5p, as well as let-7b-5p, miR-30a-3p, IL-27, and CXCL9/10/11 in TB patients’ lesion tissue and peripheral blood." (PMID 41457557, 2026). "Among the IFN-γ-inducible chemokines, CXCL9 was the most prevalent and showed the most significant results, which also was the case for the tuberculosis studies." (PMID 34501934, 2021). "IFN-γ, IP-10, IL2R, and CXCL-9 showed high expression in latent and active tuberculosis patients (p = 0.001), with a decrease in IL10 expression, and no statistical difference in IL-4 levels among all the groups (p = 0.999)." (PMID 32962082, 2020). "Additionally, correlation analysis of CXCL9/10 mRNA levels and CD4+ and CD8+ T-cell infiltration in the lungs of tuberculosis patients revealed the significant role of CXCL9/10 expression in T-cell infiltration." (PMID 39438693, 2024). "We show here that the relationship between mycobacterial antigen induced IFNγ and CXCL9 may play a role in determining disease severity in tuberculosis." (PMID 19340290, 2009). "In the mouse model of tuberculosis, depletion of neutrophils one day prior to infection did not impact overall susceptibility but had an effect on granuloma formation and resulted in delayed expression of CXCL9." (PMID 21249199, 2011). "Previously, we described elevated levels of cytokines/chemokines such as IL-18, IFN-γ, CXCL-10, CXCL-9, G-CSF, IL-6, CXCL-1, VEGF, and PDGF-BB in plasma samples of tuberculosis (TB) patients with active pulmonary disease." (PMID 37685858, 2023). "Both immunohistochemical staining and qRT-PCR indicated that the expressions of IL-27, CXCL9, CXCL10, and CXCL11 were significantly increased in tuberculosis patients, and IL-27 was significantly correlated with CXCL10 (r = 0.68)." (PMID 35785034, 2022). "In this study, we used immunohistochemistry to detect the expression levels of IL-27, CXCL9, CXCL10, and CXCL11 in patients with tuberculosis and observe their expression in the lesion." (PMID 35785034, 2022). "In previous studies, the high expression of IL-27, CXCL9, and CXCL10 in the peripheral serum, pleural effusion, and bronchial lavage fluid of tuberculosis patients used in the diagnosis and differential tuberculosis has a good performance." (PMID 35785034, 2022). "Moreover, a number of biomarkers, such as IFN-γ, CXCR3, CXCL9, CXCL10, and a combination of miRNAs, have demonstrated notable significance in the diagnosis of subclinical tuberculosis (STB)." (PMID 39274240, 2024).
liver fibrosis (25 papers, 2011 to 2025). "Increased expression of CXCL9 was also found in hepatocytes of patients with chronic hepatitis C virus infection, and its expression levels were associated with liver fibrosis." (PMID 35514751, 2022). "In the present study, we analysed the association between CXCL9-11 polymorphisms and liver fibrosis, considering LSM values, in HCV-infected patients." (PMID 28755163, 2017). "In this study, we analyzed the association between CXCL9-11 polymorphisms and liver fibrosis in HCV-infected patients." (PMID 28755163, 2017). "In conclusion, CXCL9-11 polymorphisms were related to likelihood of having liver fibrosis in HCV-infected patients." (PMID 28755163, 2017). "CXCL9 variants have been related to liver fibrosis in mice and humans." (PMID 28755163, 2017). "Additionally, CXCL9-11 polymorphisms were related to lower liver stiffness under a codominant model of inheritance, being the heterozygous genotypes also protective against hepatic fibrosis." (PMID 28755163, 2017). "The lack of binding of these miRNAs to the region surrounding these variants could lead to higher CXCL9-11 levels and, consequently, could modulate the fibrotic effect of these proteins since serum levels of CXCL9 were positively associated with the severity of liver fibrosis." (PMID 28755163, 2017). "Additionally, this work confirms the previous findings of our group in HIV/HCV-coinfected patients; suggesting that CXCL9-11 polymorphisms may play a key role in the development of liver fibrosis during CHC." (PMID 28755163, 2017). "UC-MSCs overexpressing CXCL9 were administrated to evaluate the therapeutic impact on CCl4-induced liver fibrosis." (PMID 38360740, 2024). "A series of studies have shown that CXCL9, IL15 and CCL5 up-regulated significantly in hepatocytes of HCV-infected patients and MASH patients, and existed a correlation between CXCL9 levels and liver fibrosis." (PMID 39605886, 2024). "Studies showed that CXCL9 overexpression by UC-MSCs improves their homing to the injury sites and alleviates liver fibrosis." (PMID 38360740, 2024). "CXCL9 overexpression enhanced the homing of UC-MSCs to injury sites of the liver, improving the efficacy of MSCs in treating liver fibrosis." (PMID 38360740, 2024). "Another cohort study showed that the serum concentration of CXCL9 in patients with chronic liver disease was significantly higher than that in HC patients and was positively correlated with the severity of liver fibrosis." (PMID 35514751, 2022). "Overall, CXC chemokines have been identified as the link between inflammation and angiogenesis and, especially, CXCL9 has been shown to promote liver fibrosis in animal models." (PMID 33435569, 2021). "While CXCL9 has pro-fibrotic effects in renal and skin tissue, CXCL9 has direct angiostatic and antifibrotic effects in experimental models of pancreas and liver fibrosis." (PMID 33145014, 2020). "It has been shown that the IFN- γ inducible chemokines CXCL9, CXCL10, and CXCL11 are up-regulated in patients with chronic liver diseases, and their serum levels are closely associated with the degree of hepatic fibrosis." (PMID 32887613, 2020). "The CXCL9 pathway suppresses collagen production in LX-2 cells, and CXCR3-deficient mice also demonstrated the anti-fibrotic effect of Th1 inflammation in liver fibrosis." (PMID 31369605, 2019). "It has been reported an increase of CXCL9 expression in hepatocytes of HCV-infected patients, and a correlation between CXCL9 levels and liver fibrosis." (PMID 28755163, 2017). "CXCR3 associated chemokines CXCL9 and CXCL10 were reported to be in correlation with liver fibrosis, but their roles in liver subpopulations of mice with schistosomiasis were not clear." (PMID 22905138, 2012). "Additionally, systemic administration of CXCL9 prevented the development of CCL4 induced liver fibrosis in a murine model." (PMID 35194136, 2022). "In our study, CXCL9 was up-regulated in both kidney and liver fibrosis." (PMID 35159124, 2022).